CAP2 (cyclase associated actin cytoskeleton regulatory protein 2)
Diseases named in the same sentence as CAP2 in open-access papers (continued):
Sharing a sentence is not in itself a finding about the gene and the disease.
cancer (11 papers, 2015 to 2025). A tumor composed of atypical neoplastic, often pleomorphic cells that invade other tissues. "The precise underlying mechanism through which CAP1 and CAP2 modulate cancer progression need to be further studied." (PMID 28423713, 2017). "The expression of cyclase-associated protein 2 (CAP2) is altered in several human cancers." (PMID 37707957, 2023). "Similar to CAP1, CAP2 has been implicated in cancer pathogenesis and particularly in invasiveness." (PMID 33072768, 2020). "Given that CAP2 is highly expressed in GC, transcription factors can promote gene expression in multiple cancers." (PMID 37707957, 2023). "CAP2 is overexpressed in different cancer and is an unfavorable biomarker for prognostic prediction for patients affected by breast cancer, epithelial ovarian cancer, malignante melanoma, gastric cancer, and glioma." (PMID 33072768, 2020). "To directly test for the effects of long-lasting repression of WNT-TCF targets by CAP2 we focused on cancer stem cell clonogenicity, which is WNT-TCF-dependent." (PMID 27973612, 2016). "Upregulation of CAP2/Tmprss4 is observed in various cancer types originating from pancreas, lung, breast, colon and stomach, and was found associated with poor prognosis in patients." (PMID 26309024, 2015). "Accumulating evidence has revealed that CAP2 plays a role in the progression of many cancers." (PMID 37707957, 2023). "Interestingly, cancer-linked mutations in both CAP1 and CAP2 are enriched in the N-terminal domain, with the hot spot mutations in CAP1 are located at the Arg-29 residue, which is not conserved between the two isoforms." (PMID 31718088, 2019). "Notably, we found that PANC-1 and Mia PaCa-2 cancer cells express up-regulated levels of CAP2 compared to that in the control hTERT-HPNE cells." (PMID 30894654, 2019). "Since cancer-related mutations in both CAP1 and CAP2 are more prevalent in the N-terminal part of the CAP isoforms, we compared the biochemical properties of the N-terminal region of both isoforms, which are recognized to bind F-actin and enhance cofilin-mediated filament disassembly." (PMID 31718088, 2019). "However, few studies have focused on the role of CAP2 in human cancer." (PMID 32042970, 2020). "Furthermore, we used Oncomine to confirm the CAP2 expression in different types of cancers." (PMID 28423713, 2017). "The cBioPortal analysis program identified 12 types of human cancer with significant CNAs in the chosen genes’ signature (CAP1, CAP2, CFL1, CFL2, DSTN)." (PMID 28423713, 2017). "The unusual ability of CAP2, which represents withanolide F, to repress WNT-TCF responses in human cancer cells together with its ability to alter epigenetic aspects of these cells drove us to test two related molecules for their mimicry of its effects." (PMID 27973612, 2016). "To further determine the cancer cell-intrinsic and PI3K activation-dependent immune modulating effects, we analyzed the RNAseq date from CAP2/CAP8/PC3 cell lines with two criteria: gene expressions were upregulated upon 48 h BAY1082439 treatment and downregulated 72 h after BAY1082439 withdrawal." (PMID 35013322, 2022). "High invasiveness of cancer cells overexpressing CAP1 and CAP2 correlates with their roles in stimulating the turnover of actin filaments, which is essential for cell motility via promoted formation and turnover of pro-migratory structures such as filopodia and lamellipodia, leading to metastasis." (PMID 31718088, 2019). "Moreover, ALX4, PDLIM1, CAP2 and EDIL3 have also been found to be correlated with the prognosis of cancer." (PMID 28178989, 2017).
infection (5 papers, 2021 to 2024). The state of being infected such as from the introduction of a foreign agent such as serum, vaccine, antigenic substance or organism. "Specifically, while (+)-sense RNAs generated in vitro by reovirus cores had cap1, ~40% of (+)-sense RNAs synthesized during the infection of L929 cells at 5–11 h post infection (hpi) had cap2 structures." (PMID 33668598, 2021). "The other infectious pools, AAP2, AAP3, BAP1, BAP2, BAP3, CAP1, and CAP2 might have carried the single infection of D. immitis, whose reactions putatively yielded 477-bp amplicons." (PMID 34027007, 2021). "In conclusion, we found in this study that a multi-epitope vaccine comprising Cap2, Cap3, and Cap4 epitopes effectively prevents PCV2 and PCV3 infection in mice by enhancing both cellular and humoral immune responses." (PMID 39772270, 2024). "Interestingly, after 6 h of infection, we identified genes upregulated for these virulence factors (LAC2, CAP64, CAP2, and CAS3)." (PMID 36497155, 2022).
neurological disorders (4 papers, 2015 to 2022). "Taken together, we reported for the first time altered CAP2 expression in the brain of patients with psychiatric and neurological disorders, thus suggesting that aberrant expression of this gene may contribute to synaptic dysfunction in these neuropathologies." (PMID 35163460, 2022). "Thus, CAP2 is an important actin regulator in the brain and its deletion leads to several pathological consequences that are also found in neurological disorders." (PMID 27507934, 2016). "Therefore it will be interesting to decipher the role of CAP2 in various human neurological disorders." (PMID 27507934, 2016).
myopathy (1 paper, 2019). A disease of the muscle in which the muscle fibers do not function properly. "In CAP2 mutant mice, this α-actin switch was delayed and coincided with the onset of a myopathy characterized by type IIB ring fibers and motor dysfunction." (PMID 31661040, 2019).
neurodegenerative disease (1 paper, 2022). A disorder of the central nervous system characterized by gradual and progressive loss of neural tissue and neurologic function. "Therefore, we extended our assessment of CAP2, DLG1, and ADAM10 gene and protein expression levels to the post-mortem superior frontal gyrus (SFG) of patients affected by neurodegenerative diseases such as PD and AD." (PMID 35163460, 2022).
psychiatric disorder (1 paper, 2024). A disorder characterized by behavioral and/or psychological abnormalities, often accompanied by physical symptoms. "We identified 7 genes (Cap2, Shc3, Lrrc7, Rims2, Cntnap2, Tcf20, and Trank1) associated with neurodevelopmental and psychiatric disorders that feature social impairments." (PMID 38263132, 2024).
CAP2 also shares sentences with these, for which no sentence is quoted: cardiac disease (2 papers); Arrhythmia (1); cardiovascular diseases (1); Cirrhosis (1); dementia (1); depression (1); developmental delays (1); glioblastoma (1); Heart block (1); Infertility (1); Intellectual disability (1); leukemia (1); liver disorder (1); lung carcinoma (1); lymphopenia (1); nemaline myopathy (1); ovarian carcinoma (1); preeclampsia (1); sarcoma (1); Sepsis (1).